CDC42 (cell division cycle 42)
Diseases named in the same sentence as CDC42 in open-access papers (continued):
Sharing a sentence is not in itself a finding about the gene and the disease.
lymphoma (4 papers, 2015 to 2025). A malignant (clonal) proliferation of B- lymphocytes or T- lymphocytes which involves the lymph nodes, bone marrow and/or extranodal sites. "In ALK+ ALCL the ALK-dependent downregulation of WASP contributes to the lymphoma proliferation/survival by increasing active CDC42 and MAPK pathway." (PMID 31248017, 2019). "More specifically, in human lymphomas recurrent somatic mutations have been reported only for the GTPase RHOA and for the atypical GTPase RHOH, whereas somatic mutations affecting RAC proteins or CDC42 have been described in solid tumors." (PMID 31248017, 2019). "Nonetheless, we speculate that the Rho family member Cdc42 may be associated with lymphoma cell motility and invasion and thus Cdc42 may be involved in lymphoma cell adhesion to galectin‐3 and in lymphoma cell motility involving galectin‐3." (PMID 31317621, 2019). "In this review we present the latest advances in the field with particular focus on the role of the most studied typical RHO GTPases such as CDC42, RAC1, and RHOA and the atypical RHOH in the initiation or progression of human lymphomas." (PMID 31248017, 2019). "In addition, both CDC42 and RAC1 contribute to lymphoma cell dissemination in mouse models of ALCL." (PMID 31248017, 2019).
microcephaly (4 papers, 2016 to 2023). A congenital or acquired developmental disorder in which the circumference of the head is smaller than normal for the person's age and sex. "Heterozygous variants of CDC42 have been reported in ID (with specific dysmorphic facial features and notably microcephaly and heart defects)." (PMID 36369750, 2023). "Intriguingly, despite their role in Rho-ROCK regulation and the ability to generate CIC in culture, mutations of genes encoding polarity complex proteins and interacting proteins such as CDC42 do not cause severe microcephaly in mice." (PMID 36604424, 2023). "This suggests either a positional effect, indeed, deletions may be responsible for Topologically Associating Domains (TADs) disruption and chromatin disorganization leading to the deregulation of several genes or candidate genes for microcephaly as CDC42, SKI, or RERE." (PMID 36369750, 2023).
non-alcoholic fatty liver disease (4 papers, 2017 to 2025). "In non-alcoholic fatty liver disease, hsa-miR-330 has been reported to modulate focal adhesion by targeting VEGFA and CDC42." (PMID 28570571, 2017).
osteoarthritis (4 papers, 2021 to 2022). A noninflammatory degenerative joint disease occurring chiefly in older persons, characterized by degeneration of the articular cartilage, hypertrophy of bone at the margins and changes in the synovial membrane. "Furthermore, the age-/gender-matched disease control (such as patients with osteoarthritis) was not recruited in the current study where a comprehensive analysis of CDC42 expression among RA patients, disease control, and HC was needed." (PMID 34859333, 2022).
renal cell carcinoma (4 papers, 2020 to 2023). "MiR-204, on the other hand plays tumor suppressive role by targeting CDC42 and RAB22A in nasopharyngeal and renal cell carcinoma respectively." (PMID 33790326, 2021).
rhabdomyosarcoma (4 papers, 2020 to 2025). A rare aggressive malignant mesenchymal neoplasm arising from skeletal muscle. "Notably, an in vivo study indicated that the CDC42 inhibitor promoted tumor autophagy and apoptosis in a mouse rhabdomyosarcoma xenotransplantation model." (PMID 41169985, 2025). "It has been reported that, in the metastasis of the rhabdomyosarcoma (RMS) cell line, guanine nucleotide exchange factor T(GEFT) accelerates the tumorigenicity by activating Rac1/Cdc42-PAK signaling." (PMID 36291059, 2022). "GEFT is highly expressed in rhabdomyosarcoma (RMS), which accelerates the tumorigenicity and metastasis of RMS by activating Rac1/Cdc42 signaling, but the regulatory mechanisms of autophagy and apoptosis are unclear." (PMID 34221974, 2021).
sarcopenia (4 papers, 2022 to 2025). Progressive decline in muscle mass due to aging which results in decreased functional capacity of muscles. "Using the MTA‐MO method, we identified 639 gene targets, and by analysing PPIs and querying public databases, we narrowed this list down to seven potential hub genes associated with sarcopenia (ESR1, ATM, CDC42, EP300, PIK3CA, EGF and PTK2B)." (PMID 40045692, 2025). "Applying MTA-MO to multi-omics data identified seven potential hub genes associated with sarcopenia: ESR1, ATM, CDC42, EP300, PIK3CA, EGF, and PTK2B." (PMID 41303670, 2025). "Here, we found that SELENOW KO notably decreased the protein expression of CDC42 in DEX-induced sarcopenia, whereas RAC1 was down-regulated in two sarcopenia models." (PMID 39303039, 2024). "To gain further mechanistic support, we measured the myofiber cross-sectional area (CSA), which is correlated to myofiber number and mass and decreases in conditions of sarcopenia and aging, in aged, young wild-type and young Cdc42GAP mice (which have constitutive high level of active Cdc42)." (PMID 36581635, 2022).
uterine fibroids (4 papers, 2019 to 2023). "Interestingly, the genetic variant rs10917151 in CDC42/WNT4 seems to have ancestry-specific effect on the risk of uterine fibroids." (PMID 35903355, 2022). "SNP rs10917151 (P = 1.76 × 10-24) located between cell division cycle 42 (CDC42) and the Wnt family member 4 (WNT4) genes was positively associated with uterine fibroids (A allele OR = 1.16; 95% CI: 1.13, 1.19)." (PMID 31249589, 2019).
Wiskott-Aldrich syndrome (4 papers, 2012 to 2018). Wiskott-Aldrich syndrome (WAS) is a primary immunodeficiency disease characterized by microthrombocytopenia, eczema, infections and an increased risk for autoimmune manifestations and malignancies. "WASP was originally discovered as the hematopoietically expressed product of the gene mutated in the X-linked immunological disorder Wiskott Aldrich Syndrome (WAS) and is an important downstream effector of Cdc42." (PMID 22505929, 2012). "WASP is a critical mediator of actin assembly, is activated by Cdc42, and WASP mutations lead to impaired macrophage function in Wiskott-Aldrich Syndrome." (PMID 23028423, 2012). "In support of a role for the actin cytoskeleton, peripheral blood mononuclear cells (PBMCs) from Wiskott-Aldrich syndrome (WAS) patients, where mutations in the WAS protein (WASP) results in defective Cdc42-induced regulation of the actin cytoskeleton, are resistant to CD47-induced apoptosis." (PMID 23401787, 2013). "Wiskott-Aldrich syndrome (WAS), characterised by recurrent infections and abnormal lymphocyte function is commonly caused by loss-of-function mutations in WAS protein (WASp) or in its interacting protein WIP, both of which are involved in triggering actin polymerisation downstream of Cdc42." (PMID 29337666, 2018).
asthma (3 papers, 2021 to 2025). "Defects in RAC2 regulators of actin are usually diagnosed late due to a normal immune profile, but a higher rate of specific viruses (EBV and HPV), gastrointestinal autoimmunity, asthma, and lymphoproliferation compared to CDC42 regulatory defects." (PMID 40860338, 2025). "Patients with defects in RAC2-associated regulators of actin usually present with late-onset symptoms due to normal immune profiles, but a higher rate of EBV and HPV infections, autoimmune cytopenia, asthma, and lymphoproliferation compared to defects in the CDC42 pathway." (PMID 40860338, 2025). "Specifically, it has been hypothesized that the downregulation of both genes could activate Cdc42 and Rac2 GTPases, promoting the migration of neutrophils and T lymphocytes into the lung, triggering inflammation, a mechanism that could also take place in asthma." (PMID 34442380, 2021).
autoimmune disease (3 papers, 2011 to 2022). A disorder resulting from loss of function or tissue destruction of an organ or multiple organs, arising from humoral or cellular immune responses of the individual to their own tissue constituents. "Lastly, we detected more severe liver damage in Cdc42-deficient mice in a liver-specific autoimmune disease model." (PMID 21455314, 2011). "Cdc42 deficiency results in a constitutive activation of naïve T cells, which may predispose Cdc42−/− mice to autoimmune diseases." (PMID 21455314, 2011). "Secondly, CDC42 regulated T cell differentiation into Th1 cells and Th17 cells, while it had little effect on regulating Th2 cells in autoimmune diseases; thus, we only detected Th1 cells, Th17 cells, and their secreted cytokines in RA patients instead of Th2 cells in the current study." (PMID 34859333, 2022). "Finally, Cdc42−/− mice exhibited exacerbated liver damage in an induced autoimmune disease model." (PMID 21455314, 2011). "In autoimmune disease, CDC42 can be harnessed as a decisive regulator of peripheral tolerance since it suppresses Th17 aberrant differentiation or pathogenicity, and promotes the differentiation, stability, and function of Tregs, so the CDC42 pathway may play a critical role in the immune processes." (PMID 36589282, 2022). "Albeit Cdc42−/− mice do not appear to develop spontaneous autoimmunity in the absence of infectious agents, they indeed mount more severe autoimmune responses in a N.aro-induced and T cell-mediated liver-specific autoimmune disease model." (PMID 21455314, 2011).
brain tumor (3 papers, 2011 to 2018). "Interestingly, increased activation of Cdc42, as induced by EGFL7, has been reported to reduce the survival of brain tumor‐bearing mice." (PMID 30065025, 2018).
clear cell renal cell carcinoma (3 papers, 2017 to 2023). "CDC42 plays an important role in the establishment of cell migratory polarity and persistence via its activation in clear cell renal cell carcinoma (ccRCC)." (PMID 28640862, 2017). "In clear cell renal cell carcinoma, AR suppressed circHIAT1 expression by regulating the expression of its host gene (HIAT1) at the transcriptional level, which resulted in deregulation of miR-195-5p/29a-3p/29c-3p, and increased CDC42 to enhance cell migration and invasion." (PMID 31623628, 2019).
cognitive deficits (3 papers, 2022 to 2024). "Another study reports that overexpression of CDC42 in mice can ameliorate the cognitive impairment caused by isoflurane." (PMID 37703110, 2023). "Taken together, our results provide the first evidence that Cdc42 signaling, regulated by D2R in the CPu, plays an important role in mediating spine abnormalities and motor and cognitive deficits in PD." (PMID 35415964, 2022). "CDC42 serves as a critical modifier of neural morphology by enhancing neurite outgrowth and cone protrusion and could be highly related to cognitive impairment progression in AD via the regulation of T helper (Th) cells." (PMID 39324544, 2024). "A previous report found that overexpression of CDC42 alleviates cognitive impairment in mice." (PMID 37703110, 2023). "Moreover, CDC42 is also reported to participate in mental disorders and cognitive impairment." (PMID 37703110, 2023). "Furthermore, the involvement of CDC42 in cognitive impairment is also noteworthy." (PMID 37703110, 2023). "Collectively, these results suggest that the inhibition of Cdc42 activity in D2R knockout mice is necessary for MPTP‐induced spine abnormalities as well as motor and cognitive deficits." (PMID 35415964, 2022). "Moreover, we found that constitutively active Cdc42 in the CPu was sufficient to attenuate MPTP‐induced motor coordination and cognitive deficits." (PMID 35415964, 2022).
colorectal tumor (3 papers, 2009 to 2022). "However, it has been described that this gene is also involved in tumorigenesis and tumor progression, and the aberrant expression of CDC42 has been associated to colorectal tumors." (PMID 20015360, 2009). "Similar to eIF3a, RhoA and Cdc42 represent higher expression in colorectal tumor tissues compared to adjacent normal tissues." (PMID 35300416, 2022). "APC stimulates the activity of the Cdc42- and Rac1-specific guanine nucleotide exchange factor Asef and promotes the migration and invasion of colorectal tumor cells." (PMID 24244701, 2013).
developmental delay (3 papers, 2021 to 2025). "CDC42 mutations result in a spectrum of human diseases with various clinical phenotypes, such as developmental delay, growth retardation, facial dysmorphism and more." (PMID 33323370, 2021).
faciogenital dysplasia (3 papers, 2017 to 2024). "rs55975541 in CDC42BPG, a variant with damaging PolyPhen and SIFT predictions, was found to be enriched; CDC42BPG is downstream of CDC42, the direct downstream target of the causative gene of Aarskog syndrome, FGD1." (PMID 38785976, 2024). "FGD2 is an understudied member of the FGD1 family of CDC42 GEFs, and mutations in this family have been associated with faciogenital dysplasia, a disease thought to originate from cellular migration defects during embryonic development." (PMID 31556874, 2019).
Infertility (3 papers, 2018 to 2022). "Validation of key proteins suggests that ANXA2 can be a screening biomarker for both primary and secondary infertility, whereas CDC42 and SEMG2 can be useful candidate biomarkers for primary infertility and APP for secondary infertility." (PMID 32372034, 2020). "Meanwhile, our study suggests that the CDC42 activator is a potent short-term stimulator for the activation of primordial follicles in vitro to treat infertility in POI patients." (PMID 29976179, 2018). "Western blot validation showed overexpression of ANXA2 and CDC42, and underexpression of SEMG2 proteins in primary infertility; and overexpression of ANXA2 and APP proteins in secondary infertility." (PMID 32372034, 2020). "Our results reveal that CDC42 controls the activation of primordial follicles in the mammalian ovary and that increasing the activity of CDC42 with specific activators might improve the efficiency of in vitro activation approaches, opening avenues for infertility treatments." (PMID 29976179, 2018).
malignant glioma (3 papers, 2016 to 2022). A grade III or grade IV glioma arising from the central nervous system. "Previous reports have indicated that CDC42 is a critical determinant of the migratory and invasive phenotype of malignant gliomas." (PMID 35702951, 2022). "Previous studies have already demonstrate a correlation between CDC42 activation and increased aggressiveness and invasiveness of malignant gliomas." (PMID 31231613, 2019). "In summary, our studies demonstrate that activated Cdc42 is a critical determinant of the migratory and invasive phenotype of malignant gliomas, and that its effect may be mediated, at least in part, through its interaction with IQGAP1 and phosphorylated FAK." (PMID 27486972, 2016). "Our studies demonstrate an interaction of activated Cdc42 with IQGAP1 and phosphorylated focal adhesion kinase (FAK) – an interaction which may contribute to the increased aggressiveness of and invasiveness of malignant gliomas." (PMID 27486972, 2016).
mammary adenocarcinoma (3 papers, 2008 to 2021). "We also find that in the AC, similar to mammary adenocarcinoma cells, the actin regulator and CDC-42 effector WSP-1 (N-WASP), functions downstream of CDC-42 to promote F-actin formation." (PMID 26765257, 2016). "It has been shown that over-expression of IQGAP1 enhances the capacity of human breast adenocarcinoma MCF-7 cell for transmembrane migration by up-regulating the expression active CDC42 and Rac1." (PMID 19036171, 2008). "A similar result was seen in mammary adenocarcinoma cells, suggesting that WASP proteins are not the sole effector of Cdc42 responsible for invadopodia formation." (PMID 26765257, 2016).
myelofibrosis (3 papers, 2020 to 2023). A partial or complete replacement of the bone marrow stroma by fibrous tissue. "Another recent report suggests that mutation in the CDC42 gene in a human patient is found to be associated with myelofibrosis in adulthood." (PMID 33672558, 2021). "Here, we describe two affected siblings withinfantile myelofibrosis and myeloproliferation that share a common de novo mutationin the Rho GTPase CDC42 (Chr1:22417990:C>T, p.R186C) due to paternal germlinemosaicism." (PMID 32303876, 2020). "Conditional deletion of Cdc42 in the mouse hematopoietic system led to a rapidly fatalmyeloproliferative disorder.Finally, a different variant in CDC42 (Y64C)in a human patient has been associated with myelofibrosis observed in adulthood." (PMID 32303876, 2020). "The data reported here extend the phenotypic spectrumresulting from CDC42 R186C mutations and suggest that patients presenting withcongenital myeloproliferation or myelofibrosis be screened for this germlinemutation." (PMID 32303876, 2020). "Our findings complement recent studies of patients with a distinctdisorder involving immune deregulation and suggestthat CDC42 dysfunction can result in congenital myelofibrosis and myeloproliferationpresenting during infancy." (PMID 32303876, 2020).
myeloproliferative disease (3 papers, 2015 to 2024). "CDC42 deletion in the mouse bone marrow led to a rapidly fatal myeloproliferative disorder." (PMID 33672558, 2021).
nephrotic syndrome (3 papers, 2018 to 2020). A collection of symptoms that include severe edema, proteinuria, and hypoalbuminemia; it is indicative of renal dysfunction. "Mutations in proteins influencing the actin dynamics (e.g., α-actinin-4, INF2, CDC42) are known to cause kidney injuries including nephrotic syndrome or FSGS31–34." (PMID 30154411, 2018). "As Rac1, Cdc42, and RhoA are implicated in the pathogenesis of nephrotic syndrome in mice and humans, we examined whether these Rho GTPases interact with PLCE1 in cultured podocytes." (PMID 32238860, 2020).
osteopetrosis (3 papers, 2016 to 2024). Osteopetrosis, also known as marble bone disease, is a descriptive term that refers to a group of rare, heritable disorders of the skeleton characterized by increased bone density on radiographs. "In contrast to Cdc42 loss-of-function or WASP deletion, global and osteoclast-specific deletion of Hem1 led to severely reduced resorption in vitro as well as in vivo leading to an osteopetrosis-like phenotype." (PMID 38582757, 2024).
ovarian tumor (3 papers, 2015 to 2021). "We also measured the expression of CDC42 variants by qPCR in 18 normal ovarian tissues and 29 malignant ovarian tumor tissues." (PMID 26336992, 2015). "Further, CDC42-v2 was observed to have inhibitory effects on ovarian tumor cell growth, colony formation in soft agar and invasiveness." (PMID 26336992, 2015). "To answer these questions, we first examined whether ectopic expression of CDC42-v2 affected ovarian tumor cell behaviors." (PMID 26336992, 2015). "We also found that CDC42-v2 was downregulated in ovarian tumor cells." (PMID 26336992, 2015).
RASopathy (3 papers, 2018 to 2022). Developmental syndromes caused by germline mutations (or in rare cases by somatic mosaicism) in genes that alter the Ras subfamily and mitogen-activated protein kinases that control signal transduction. "They demonstrated that specific CDC42 mutations are associated with a RASopathy-like phenotype." (PMID 29734338, 2018). "Our data point to a novel aspect in the molecular pathogenesis of RASopathies as we uncovered RIT1 as regulator of cytoskeletal changes through the RHO GTPases RAC1 and CDC42 and their effector PAK1." (PMID 29734338, 2018). "CDC42 and RALA are components of a non‐canonical Ras pathway, but neither functional nor clinical data have yet sufficiently classified them as RASopathy genes." (PMID 35266292, 2022).